CD4 (CD4 molecule)
Diseases named in the same sentence as CD4 in open-access papers (continued):
Sharing a sentence is not in itself a finding about the gene and the disease.
tumor (continued). "Mechanistically, CTLA-4 inhibition reduces CD4+ Treg proliferation and induces the expansion of a Th1-like CD4+ effector populations, while inhibiting PD-1 reduces T-cell exhaustion and increases CD8+ tumor infiltrating subsets." (PMID 34512641, 2021). "Tumor tissues and matched normal fallopian tubes were immunostained for CD3+, CD8+, and CD4+ T cells on corresponding tissue microarrays and the numbers of TILs were counted using the NIH ImageJ software." (PMID 33718143, 2021). "In contrast, anti-IFN-γ dramatically reduced the infiltration of CD4+- and CD8+ T cells into tumours." (PMID 33925140, 2021). "The estimated levels of CD4+ (p = 0.0012) and CD8+ T cells (p = 0.017) via the tumor immune estimation resource were higher in patients with SARC with better overall survival." (PMID 33597971, 2021). "This further layer of complexity, however, rather than increasing the number of players in the process of tumor immunoediting enlightens the opposing role of CD8+ cytotoxic lymphocytes and CD4+ Tregs." (PMID 34787568, 2021). "This efficacy is dependent on CD4+ and CD8+ T cells while being NK-cell-independent, demonstrating the boost that these arming factors give to tumor-infiltrating T cells, allowing them to overcome the immunosuppressive tumor environment and clear tumors." (PMID 34445759, 2021). "Once in the nucleus, the bacterial plasmid is expressed in order to deliver its tumor antigens, which are then presented to T cells via MHC I and II to trigger the activation of CD8+ and CD4+ T cells." (PMID 34885150, 2021). "The TAMs in KRAS KO tumors were skewed toward M1 polarization, while tumor-infiltrating lymphocytes (TILs) were dominated by CD8 cytotoxic T cells (40%) and natural killer T (NKT) cells (40%), compared to CD4 helper T cells (20%)." (PMID 33674596, 2021). "A retrospective study of colorectal cancer patients who had received preoperative RFA to liver metastases showed increased number of CD4 and CD8 TILs and increased PD-L1 expression in the resected primary tumours." (PMID 34733287, 2021). "To also identify systemic immune-related events that were affected by chemotherapy, we analyzed the same CD4+ and CD8+ lymphocyte subsets in the spleens of tumor-bearing mice." (PMID 34201054, 2021). "The in vivo study revealed that melatonin suppressed the expressions of YAP and PD-L1 in tumor tissues, and administration of melatonin decreased infiltrations of TAM and MDSC while increasing CD8+ and CD4+ T cells." (PMID 34073318, 2021). "Circulating CD4+T cells can target cancer cell surface antigens and activate peripheral blood CD8+T cells to enter the tumor microenvironment, which can activate the function of killing cancer cells." (PMID 34258299, 2021). "Specifically, CD4+ and CD8+ T cells recognize tumor antigens and have been proven to induce tumor cell apoptosis." (PMID 34149937, 2021). "In the tumor, hetIL-15-stimulated NK, CD8+ and CD4+ T cells show increased proliferation, survival, and cytotoxic commitment, with high levels of IFN-γ and granzyme B secretion." (PMID 33671252, 2021). "A great amount of focus has been on improving survival, proliferation, and effector function of CD4+ and CD8+ T cells, but other immune cells such as NK cells also readily respond to IL-2 and are important for mediating cytotoxicity towards tumor cells." (PMID 34790830, 2021). "In contrast to total CD4+cells, treatment with LFPRLR SMO reduced the percentage of Tregs within the tumor microenvironment." (PMID 34375938, 2021). "Analysis of infused batches of tumor-specific T cells revealed the presence of polyclonal tumor-reactive CD8 T and CD4 T cells." (PMID 34140957, 2021).
tumor (continued). "On day 15, BM infiltration rate was similar after depletion of CD4+ or CD8+ T cells, whereas depletion of Gr-1+ myeloid cells significantly reduced tumor infiltration by 1.9-fold from 31.0% to 16.3% compared to isotype control (p = 0.0034)." (PMID 34638774, 2021). "Tumor RNA sequencing analysis confirmed pathways of inflammation and CD4 and CD8 T-cell activation to be common between the PD-1 ab-treated and PD-1cKO mice and a dominant IFNγ response in the tumor microenvironment." (PMID 34912335, 2021). "In our study, anti-PD1 mAb treatment induced a modest increase in the percentage of CD4+ and CD8+ T cells in the tumor beds." (PMID 33754054, 2021). "Regorafenib, multiple kinase inhibitor, decreased tumor CD31-positive angiogenesis, the total number of TAMs, but increased M1/M2 ratio and infiltration of tumor by CD4+ and CD8+ T cell in mouse model of HCC." (PMID 34209679, 2021). "In a clinical trial of a murine IgG1 anti- OX40/CD134 MoAb in patients with late-stage cancers, transient expansion of effector CD4+ T, CD8+ T, and NK cells was observed in some patients who showed tumor regression." (PMID 35008305, 2021). "When we compared matched baseline and on-treatment samples in our small cohort of samples, we observed a reduction in numbers of CD4 + and CD8 + T-cells, in particular in tumours in the pCR group." (PMID 33983492, 2021). "IL-1β inhibits tumor growth by promoting tumor cell death; this is accomplished by priming CD8+ T cells or stimulating CD4+ T cells toward Th1 response." (PMID 34829795, 2021). "In contrast, leucocytes were quite rare inside the tumor nodules except for gal-9-KO tumors at cycle 4 for which a substantial number of CD45+, CD4+ and CD8+ leucocytes were visible inside the nodules." (PMID 33664349, 2021). "The areas with specific CD4+T cells, CD8+T cells, and CD19+B cells within the tumor microenvironment were measured in paraffin sections by immunohistochemistry and analyzed by Image-Pro Plus." (PMID 34258299, 2021). "Findings from the study indicated that subcutaneous vaccination with H2O2-inactivated Salmonella enhanced splenic T cell activation and increased CD4+ and CD8+ T cell infiltration into the tumor tissue." (PMID 34829795, 2021). "It was also noted that with the reduction in the Treg cell population, the percentages of Th1 cells (CD4+IFN-γ+) and IFN-γ+ CD8 T cells were increased in tumours, while that of Th2 cells (CD4+IL-4+) was almost unaffected." (PMID 33654093, 2021). "Metronomic paclitaxel administration leads to CD4 and CD8 T cell infiltration increase into tumor tissues and a reduction in the number of immunosuppressive cells." (PMID 34066606, 2021). "This revealed that pathways related to IL-2, CD4+ T cell memory formation and stimulation of CD8+ T were enriched in tumor-infiltrating T cells treated with hsBCL9CT-24." (PMID 34417435, 2021). "TAM-s, which secrete anti-inflammatory and immune suppressive cytokines (e.g., TGFβ and IL10), enhance the expansion of immune suppressive CD4+ Treg cells, inhibit the functions of CD8+ cytotoxic T and NK cells and similarly to tumor cells also express IDO1." (PMID 35366268, 2021). "These donor cells were distributed unevenly in each tumor, and AAA-CD4+ T cells were observed in more areas compared to auto-CD4+ T cells." (PMID 34625113, 2021). "Activated eosinophils can secrete chemokines CXCL9, CXCL10, CCL17, and recruit CD4+T and CD8+T cells into the tumour microenvironment." (PMID 35003085, 2021). "For example, CD4+ FOXP3+, CD4+, Th2 cells, macrophages, and MDSC cells promote growth by activating synergistic pathways between the immune microenvironment and tumor cells." (PMID 34205709, 2021). "On the other hand, there was a positive correlation between the density of CD4+ TILs and parameters such as pT, lymphovascular invasion, pN, and TNM stage, which are important indicators of tumor progression." (PMID 34938330, 2021).
tumor (continued). "We also observed that activated Prkd2-S707A/S711A CD4+ and CD8+ T cells have significantly reduced IFNγ production ex vivo suggesting that T cell PKD function also plays a significant role in tumor growth." (PMID 35046933, 2021). "The relationships between 6 immune cell types (B cells, CD8 + T cells, CD4 + T cells, macrophages, neutrophils and myeloid dendritic cells) and CDK19 expression were determined by Spearman tests (tumor purity adjusted)." (PMID 34649520, 2021). "There is a mutually supportive relationship between CD4+ and CD8+ T cells; both cell types are components of the adaptive arm of the immune system and rely on antigen expression to initiate anti-tumor immunity." (PMID 33669271, 2021). "PSA-TRICOM has also been evaluated as intraprostatic administration, resulting in an increased CD4+ and CD8+ cells infiltrate in tumor biopsies, determining PSA stability in 10/19 patients." (PMID 34207536, 2021). "CD4+ Th-derived cytokines are required for full activation of CD8+ T cells, which can give rise to tumor-specific CTLs35,57." (PMID 34262035, 2021). "T cells have an essential role in tumor immunity, and CD244 is expressed by CD4+ and CD8+ T cells, thereby regulating the anti-tumor effect of these cells or mediating immune escape in mice." (PMID 33841431, 2021). "Kynurenine catabolized from tryptophan within tumor cells can promote Treg cell function and numbers by activating kynurenine aryl-hydrocarbon receptor (AHR) in CD4+ T cells." (PMID 34566954, 2021). "CXCL16 enhances IFNγ production by NKT cells, while IL-12 enhances IFNγ secretion by iNKT cells, NK cells, Th1 CD4+ and CD8+ T cells, providing a positive feedback loop to support a robust anti-tumor immune response." (PMID 34680322, 2021). "CD27, a member of the tumor necrosis factor receptor family, is present in CD4, CD8 T lymphocytes and NK cells, plays a significant role in tumor immunotherapy." (PMID 33766042, 2021). "Several studies have suggested that CD4+ T cells are needed to activate CD8+ T cells; their population has also been suggested to have a direct anti-tumor effect." (PMID 34208855, 2021). "On the other hand, the regulatory T cells (Treg) (CD4+CD25+FoxP3+) cell population was significantly reduced in the spleen and tumor of the BME-fed mice, suggesting its immunomodulatory role." (PMID 34765739, 2021). "In conclusion, our research shows that the systemic inflammatory markers, serum CD4 and CD19 and tumor infiltration of CD4+T cells, CD8+T cells, and CD19+B cells can predict the prognosis of GC patients." (PMID 34258299, 2021). "In vitro and in vivo studies have demonstrated that IL-10+ Bregs induced by mouse tumor cells are able to reduce IFN-γ production by antigen-specific CD8+ and CD4+ T cells as well as NK activation." (PMID 33995344, 2021). "Over the course of the experiment, 4–5 mice per time point were analyzed for tumor load, CXCR5 expression of tumor cells, and total CD4 and CD8 T cell numbers in BM and spleen." (PMID 33431832, 2021). "In, the immune cells (tumor-infiltrating cytotoxic T lymphocytes CD8 (CD3+CD4−CD8+) and helper T lymphocytes CD4 (CD3+CD4+CD8−) were analyzed in untreated distant tumors from different groups." (PMID 34993150, 2021). "This prompts the infiltration of tumor-infiltrating lymphocytes (TILs) and other peripheral blood mononuclear cells (PBMC) to the affected area of the skin to destroy the malignant CD4+ T-cells." (PMID 34204115, 2021). "However, FATS deficiency did not reduce the tumor burden in the context of CD4+ T cell depletion." (PMID 34262035, 2021). "This suggests that CD4+ T cells, CD8+ T cells, and NK cells all play a role in inhibiting LL/2-tdTomato/Luc tumor growth in vivo." (PMID 34411144, 2021). "A total of 372 patients were divided into two subgroups stratified by the median density of each subset, i.e., CD3+, CD4+, CD8+, CD45RO+, and CD56+ immune cells, in tumor stroma into higher half (n = 186) and lower half (n = 186)." (PMID 34572935, 2021).
tumor (continued). "In this study, we observed increased infiltrations of CD4+, CD8+ T lymphocytes, and CD11b+CD11c+ DC in a CXCL13-expressing 4T1 tumor microenvironment." (PMID 35693216, 2021). "The population of CD45+, CD3+, CD4+, CD8+, and regulatory T (Treg) cells was estimated in the peripheral blood or tumor." (PMID 34178691, 2021). "In mice fed with GF-EPS, CD4+ and CD8+ T cells were found to transfer tumor-inhibitory activity to C26-bearing mice, suggesting the ability to modulate an immune response plays a crucial role in the anticancer activity of GF-EPS." (PMID 34681911, 2021). "A recent consensus statement by flow cytometry experts recommended the additional assessment of abnormalities that are more specific for neoplasia, such as dim expression of CD3, CD4, and CD45, or increased light scatter properties." (PMID 33673033, 2021). "Frequently defined by the expression of CD4+ and FOXP3+, Tregs have a high frequency in tumor and are correlated with poor outcomes in cancer patients." (PMID 34541363, 2021). "Compared to LG patients, cases with HG tumor budding exhibit significantly lower densities of CD3+, CD4+ and CD8+ T cells (p = 0.0003, 0.003 and 0.004 respectively)." (PMID 33806316, 2021). "In this study, we found that tumor cells of MF/SS expressed CD147 and that expression levels in tumor cells were much higher than those in CD4+ T cells in healthy controls." (PMID 34360654, 2021). "The proportion of the Th2 subset (CD4+GATA3+) was decreased after RFA and cryo-thermal therapy compared to that of tumor-bearing mice, and the level of Th2 cells in the cryo-thermal treated group was much lower than that in the RFA group." (PMID 34576115, 2021). "To investigate the role of tumor microenvironment (TME) in regulating CD4+ T-cell lineages, we performed whole-genome bisulfite sequencing (WGBS) to decipher the DNA methylome of CD4+ T cells isolated from tumor and blood from 5 newly diagnosed GBM patients." (PMID 34012510, 2021). "In tumor infiltrating T lymphocytes cells, CD8 T and CD4 Th1 cells typically contribute to immune-mediated tumor suppression." (PMID 33407498, 2021). "This position is additionally supported by the results obtained for the distribution of CD3+ and CD4+ cells, the number of which was the highest in early TNM stages and constitutively decreased with clinical advancement of the tumor." (PMID 33625532, 2021). "We found that the number of apoptotic tumor cells increased along with the increased number of CD8+ T cells within the tumors, whereas the number of CD4+ T cells and FoxP3+ regulatory T cells (Tregs) decreased with topical IMQ." (PMID 34439104, 2021). "Blockage of PD-L1 can restore IFNγ/TNF-α production in BTLAPD-1 tumor CD4+T cells, but partially inhibit the activation of BTLAPD-1 CD4+T cells." (PMID 34869376, 2021). "IFN-γ production by in vitro-stimulated CD4+ TILs, CTLs, γδ T cells, and MAIT cells were proportionally similar in fresh and cryopreserved tumor portions, albeit the latter displayed lower levels." (PMID 34067849, 2021). "However, though often considered tumor permissive, the deletion of Tregs accelerates tumor formation in transgenic models of murine PDAC, associated with a loss of myCAFs within the TME, as well as an increase in immunosuppressive myeloid cells and pathological CD4+ T cell responses." (PMID 34680235, 2021). "Tregs are CD4+ CD25+ T cells that play a central role in suppressing the TAIR, and their accumulation in the microenvironments of the tumor and TDLNs portends a poor prognosis in CRC." (PMID 34950576, 2021). "In particular, CD8+ tumor-infiltrating lymphocytes (TILs), T helper 1 (TH1) CD4+T cells and macrophages migrate into the tumor microenvironment, and elicit IFNγ secretion and anti-tumor effect." (PMID 34671202, 2021). "We assigned ITH scoring by calculating the standard deviation (SD) of CD4+ and CD8+ T-cell densities from ten regions of each tumour." (PMID 33431814, 2021).
tumor (continued). "The selectively released PM down-regulated the expression of PD-L1 protein by effectively inhibiting tumor mitochondria function, resulting in a significant increase of CD3+, CD4+, and CD8+ infiltration in the tumors." (PMID 34794446, 2021). "Contributing to providing insight for immunotherapeutic treatment in THCA, the tumor immune infiltrates of THCA, including B cells, CD4+ T cells, CD8+ T cells, neutrophils, macrophages and dendritic cells, were analyzed via the TIMER platform." (PMID 34737762, 2021). "Along with the inability of CD8+ cells to control tumor growth due to reduced cytotoxicity, pro-tumoral signaling that supports CLL cells’ survival is also induced by the CD4+ T cell fraction in CLL." (PMID 34209724, 2021). "Individual gene expression analysis of all 319 correlated genes of the ‘green’ module revealed distinct expression differences between macrophages and CD4+ and CD8+ T cells and in gene regulation between tumor and non-tumor cells." (PMID 33918618, 2021). "In a distinct tumor Ag model, CD39+ CD4 and CD8 TILs were found to be specific for HPV Ags in HPV-induced malignancies." (PMID 33332284, 2021). "In this study, MLKL mRNA electroporation in vivo was demonstrated to induce CD4+ and CD8+ T cell responses directed against tumor antigens that were responsible for tumor control." (PMID 34490126, 2021). "In tumors such as non-small-cell lung cancer, clear-cell carcinoma, and hepatocellular carcinoma, TIM-3 is not only found on the CD4+ and CD8+ TILs, but also expressed on the tumor cells." (PMID 34359588, 2021). "To present the changes of the immune cells in TME after the NRT cell therapy, we investigated the infiltration of CD4 + /CD8 + T cells, TAMs and Treg cells in single-cell suspensions from primary mouse tumour tissue through flow cytometry." (PMID 34291357, 2021). "ARG1-containing exosomes suppress proliferation of CD4+ and CD8+ T-cells in vitro and in vivo in OvCa mouse models by distributing ARG1 from tumor cells to antigen-presenting cells in secondary lymphoid organs." (PMID 34248988, 2021). "Our data confirm that TIGIT is frequently expressed in T lymphocytes within the tumor microenvironment of CHL8 and TIGIT expression seems to be related to CD4+ activated T lymphocytes surrounding the malignant HRS cells." (PMID 33782477, 2021). "In recent years, some biomarkers in the blood circulation have shown value in predicting the response of patients to immunotherapy, such as PD-1+CD8+ T cells, CD4+ T cells, TCR repertoire, cell-free DNA, circulating tumor cells, and cytokines." (PMID 34239620, 2021). "CD4+ T helper-1 (Th1) boosts T-cell activation, CTL toxicity, and anti-tumor activity of macrophages and NK cells via the production of pro-inflammatory cytokines." (PMID 34485117, 2021). "Pro-tumoral M2 macrophages are prevalent in the tumor microenvironment (TME) of UM whereas CD4+ and CD8+ lymphocytes are restricted to the periphery of the tumor and where they cannot attack tumor cells." (PMID 34830841, 2021). "CD4+ and CD8+T cells are an important part of the tumor microenvironment and kill tumor cells by exerting specific immune responses." (PMID 35127503, 2021). "The authors also found that ICI therapy was more effective when tumor cells express both MHC-I and MHC-II neoantigens, i.e., they are targets for both CD8+ and CD4+ cells." (PMID 33777008, 2021). "T helper cells (CD4+) and cytotoxic T cells (CD8+) are the two main subpopulations of T cells that control and shape the immune responses in the tumor microenvironment (TME)." (PMID 34440139, 2021). "We also found that Poly6 treatment increased the production of TNF-α or IFN-γ producing CD4 and CD8 T cells in tumor tissue, which have anticancer effector functions." (PMID 33499256, 2021). "Eμ-myc expression reduced peripheral CD4 and CD8 T cells in pre-tumor spleens of both IL6+/+;Eμ-myc and IL6-/-;Eμ-myc mice." (PMID 33651821, 2021).